SMARCA4 (SWI/SNF related BAF chromatin remodeling complex subunit ATPase 4)
Diseases named in the same sentence as SMARCA4 in open-access papers (continued):
Sharing a sentence is not in itself a finding about the gene and the disease.
gastric cancer (continued). "Mutations have been described in other members of the same family, such as ARID1A in around 50% of ovarian clear cell carcinomas and in gastric cancer, and SMARCA4/BRG1 in lung tumors." (PMID 22675518, 2012). "Expression of SMARCA4 and SMARCE1 in gastric cancer as illustrated by immunohistochemistry." (PMID 36916408, 2023). "Meanwhile, considering the poor prognosis of undifferentiated/dedifferentiated gastric carcinoma, it is recommended to carry out immunohistochemical examinations of SWI/SNF complex subunits, especially SMARCA2 and SMARCA4, further to implement stratification for precise and individualized treatment." (PMID 36464671, 2022). "Among these tumor suppressor genes, SMARCA4 encodes a component of the SWI/SNF chromatin remodeling complex, and significant deletions have not previously been reported in gastric cancer." (PMID 28426752, 2017). "SMARCA4-altered gastric cancers may do not benefit from chemotherapy and had poor outcomes." (PMID 38877473, 2024).
pancreatic cancer (31 papers, 2012 to 2025). "Of note is that, among these putative transcriptional factors present at the 5′ region of the PRUNE_1 gene, we found mutations in SMARCA4 that are available in a significant frequency of MB and pancreatic cancers and in many other tumor subtypes." (PMID 34745995, 2021). "Re-expression of SMARCA4 in SMARCA4-deficient pancreatic cancer cell lines PANC-1 and Hs700T led to senescence and reduced cell growth." (PMID 31769422, 2019). "To independently confirm these findings, we carried out the converse set of experiments, namely restoring SMARCA4 expression in SMARCA4-deficient pancreatic cancer cells, and evaluating altered chemo sensitivities." (PMID 29515757, 2018). "The human pancreatic cancer cell line PANC1 is deficient in SMARCA4 protein, in part from a genomic rearrangement at that locus." (PMID 29515757, 2018). "Similar to ARID1A, SMARCA4 is highly mutated in pancreatic cancer." (PMID 31238554, 2019). "In addition to a panel of SMARCA2-deficient tested cells, SMARCA2-deficient pancreas carcinoma HuP-T4 cells were dependent on SMARCA4." (PMID 31769422, 2019). "Restoration of SMARCA4 expression in a different SMARCA4-deficient pancreatic cancer cell line, Hs700T, led to very similar findings, with the most substantial impact being reduced sensitivity to the DNA-damaging agents cisplatin (28-fold), oxaliplatin (33-fold), and irinotecan (7.4-fold)." (PMID 29515757, 2018). "Re-expression of SMARCA4 in SMARCA4-deficient pancreatic cancer cell lines reduced cell growth." (PMID 27999365, 2016). "In the present review, we summarized the mutations of epigenetic regulators, including ARID1A, SMARCA2, SMARCA4, KDM6A, KMT2C, KMT2D, and BRD4 in GI cancers—in particular, pancreatic cancer—and found these regulators to be frequently mutated." (PMID 31238554, 2019). "We then challenged the SMARCA4-knockdown cells to a variety of chemotherapeutic agents, focusing on those that have been evaluated clinically in the treatment of pancreatic cancer." (PMID 29515757, 2018). "ARID1A, ARID1B, PBRM1, SMARCA2, and SMARCA4 are all components of the SWI/SNF complexes, and were shown by genomic sequencing studies to be mutated in pancreatic cancer." (PMID 27999365, 2016). "Putative DNA binding subunits ARID1A, ARID1B, and PBRM1, enzymatic subunits SMARCA2 and SMARCA4, and ARID2 have been shown to be mutated in pancreatic cancer." (PMID 27999365, 2016). "Interestingly, SMARCA4 played both tumor-suppressive and oncogenic roles at distinct stages of pancreatic cancer formation." (PMID 36902184, 2023). "On tissue NGS of immunotherapy-treated, SWI/SNF-altered pancreatic cancer patients, 7 patients harbored an ARID1A alteration (77%); 2 harbored an ARID1B mutation (22%); 3 harbored a SMARCA4 mutation (33%); 1 harbored a SMARCB1 mutation (11%); and 1 harbored a PBRM1 mutation (11%)." (PMID 34375311, 2021). "Furthermore, knockdown of SMARCA4 in pancreatic cancer cell lines PANC-1 and MIA PaCa-2 led to reduced growth in vitro and in vivo." (PMID 31769422, 2019). "Several studies indicated that SMARCA4 expression is increased in pancreatic cancer tissues." (PMID 31769422, 2019). "In pancreatic cancer, recent whole genomic sequencing also revealed pathogenic mutations and structural variants in several epigenetic regulator genes including KDM6A, ARID1A, ARID1B, PBRM1, SMARCA2, SMARCA4, and MLL2." (PMID 27999365, 2016). "Undifferentiated pancreatic carcinomas show a higher frequency of abnormalities in SWI/SNF complex subunits, such as ARID1A and SMARCA4, and increased expression of EMT-related markers compared to ductal adenocarcinomas." (PMID 40866717, 2025). "Results revealed that the mRNA levels of SMARCA3, SMARCA4, HELLS were significantly upregulated in patients with pancreatic cancer, while the mRNA levels of SMARCA2 and SMARCAD1 were downregulated." (PMID 34315468, 2021).
pancreatic cancer (continued). "In summary, the current analysis suggests that a subgroup of patients with pancreatic cancer and alterations in SWI/SNF complex chromatin remodeling genes, such as ARID1A, ARID1B, PBRM1, SMARCA4, and SMARCB1, can respond to ICI." (PMID 34375311, 2021). "The nonimmunotherapy-treated SWI/SNF-altered pancreatic cancer patients harbored 5 ARID1A alterations (83%) and 1 SMARCA4 mutation (17%); none possessed more than 1 SWI/SNF complex alteration." (PMID 34375311, 2021). "PPP1R1B, SMARCA4, and TGFB1 have well-described roles in the pathogenesis of pancreatic cancer." (PMID 34009124, 2021).
colon cancer (28 papers, 2009 to 2025). "We presented a rare case of undifferentiated colonic neoplasm with loss of SMARCA4 protein expression and germline SMARCA4 mutation." (PMID 33836796, 2021). "We reported a rare case of a 61-year-old man diagnosed with undifferentiated colonic neoplasm with a heterogeneous pattern of loss expression of SMARCA4 and germline SMARCA4 mutation, as well as predictive markers for potential immunotherapy or targeted therapy." (PMID 33836796, 2021). "Many solid tumors have mutations in SWI/SNF that cause PRC2 hyperactivity; for example, colon cancer cells can have ARID1A and SMARCA4 driver mutations." (PMID 41000734, 2025). "In a model of colon cancer, SMARCA4 and PRMT1 were shown to promote CRC progression cooperatively via EGFR signaling." (PMID 38472198, 2024). "The involvement of NOTCH3 and SMARCA4 in the regulation of colon cancer was proved via direct interaction with endogenous and exogenous co‐IP and GST‐pulldown experiments." (PMID 35900231, 2022). "The protein expression patterns of NOTCH3 and SMARCA4 may be closely related to the prognosis of patients with colon cancer." (PMID 35900231, 2022). "In addition, the possible targeting factors of NOTCH3 and SMARCA4 in colon cancer cells were screened through RNA‐seq, and, for the first time, we identified that MUC5AC and MUC2 may be the targeted factors for the co‐regulation of NOTCH3 and SMARCA4 interaction." (PMID 35900231, 2022).
Coffin-Siris syndrome (27 papers, 2012 to 2026). "The clinical data and molecular genetic test results of a newbron with Coffin-Siris syndrome involving a pathogenic variant in the SMARCA4 gene were retrospectively analyzed, and the related literatures were reviewed." (PMID 39906730, 2024). "Our objective was to examine the clinical and genetic features of Coffin-Siris syndrome resulting from a pathogenic variant in the SMARCA4 gene." (PMID 39906730, 2024). "Otolaryngologic, facial and finger features in patients with Coffin-Siris syndrome in SMARCA4 gene variant." (PMID 39906730, 2024). "A few patients with Coffin-Siris syndrome in SMARCA4 gene variant had the same variation c.DNA, including c.2681C > T, c.2653C > T, c.2654G > A." (PMID 39906730, 2024). "Germline missense mutations in the BAF swi/snf chromatin remodeling subunit SMARCA4 are associated with neurodevelopmental disorders, including Coffin Siris Syndrome (CSS)." (PMID 33799280, 2021). "Very recently, several helicase domain containing Snf2 proteins, including SMARCA2 and SMARCA4, were identified to cause Nicolaides-Baraitser syndrome and Coffin-Siris syndrome." (PMID 22888405, 2012). "Heterozygous missense mutations and in-frame deletions in the SMARCA4 helicase subunit have been reported in individuals with a mild phenotypic spectrum of Coffin-Siris Syndrome, characterised by developmental delay, coarse facial features and hypoplastic distal phalanges." (PMID 33799280, 2021). "Interestingly, germline variants of SMARCB1 and SMARCA4 have been identified also in patients with Coffin-Siris syndrome three (CSS3, OMIM #614608) and four (CSS4, OMIM #614609)." (PMID 33692948, 2021). "The current EpiSignTM BAFopathy episignature encompasses several subtypes of Coffin–Siris syndrome associated with multiple genes (ARID1A, ARID1B, SMARCB1, SMARCA4) and Nicolaides–Baraitser syndrome (SMARCA2)." (PMID 36430143, 2022). "In contrast to other genetic disorders related to PVs in SMARCB1 and SMARCA4 such as Coffin-Siris Syndrome, RTPS1&2 are characterized by a predominance of truncating PVs, terminating transcription thus explaining a specific cancer risk." (PMID 33532948, 2021). "The same corresponding mutations occurring in SMARCA1, SMARCA4, and SMARCA2 (components of a closely related chromatin remodeling complex known as SWI//SNF) cause Schimke immune-osseous dysplasia, Coffin–Siris syndrome and Nicolaides–Baraitser syndrome." (PMID 33981601, 2021). "The equivalent arginine residue in SMARCA4, which is one of the catalytic subunits of the BAF complex, has been implicated in the rare genetic disorder Coffin-Siris syndrome." (PMID 32543371, 2020). "Germline mutations in SMARCA4, SMARCB1, and other SWI/SNF components also cause Coffin-Siris syndrome (CSS), a developmental disorder primarily characterized by developmental delay and intellectual and physical disabilities." (PMID 27866340, 2017). "In addition to our case, we also retrieved 22 cases of Coffin-Siris Syndrome in SMARCA4 gene variation, which is a congenital multi-system dysfunction syndrome characterized by abnormal appearance and developmental retardation." (PMID 39906730, 2024). "A rare genetic disorder associated with the SMARCA4 and SMARCB genes is known as Coffin-Siris syndrome (CSS)." (PMID 35163487, 2022). "First described in 1970, Coffin–Siris syndrome is an intellectual disability disorder that is caused by mutations in genes encoding individual subunits of the BAF (BRG1/BRM-associated factor) complex, including ARID1A, ARID1B, SMARCA2, SMARCA4 (BRG1), SMARCB1 (INI1), and SMARCE1 (BAF57)." (PMID 26103525, 2015). "Mutations in other genes involved with the SWI/SNF complex such as ARID1A, SMARCA2, SMARCA4, SMARCB1 and SMARCE1 are also responsible for Coffin-Siris syndrome." (PMID 26376624, 2015).
Coffin-Siris syndrome (continued). "Sequence variants in other BAF complex genes are associated with other neurodevelopmental disorders including SMARCC1/2, PBRM1, ARID1A/B and SMARCA4 in ASD, PBRM1 and ARID1B in schizophrenia, SMARCB1 in Kleefstra syndrome, and ARID1A/B, SMARCA4, SMARCB1, and SMARCE1 Coffin-Siris syndrome (CSS)." (PMID 31288860, 2019).
undifferentiated carcinoma (26 papers, 2019 to 2026). A usually aggressive malignant epithelial neoplasm composed of atypical cells which do not display evidence of glandular, squamous, or transitional cell differentiation. "Gastric SMARCA4-deficient undifferentiated carcinoma is an exceptionally rare and highly aggressive malignancy characterized by loss of SMARCA4 expression." (PMID 42052459, 2026). "SMARCA4-deficient undifferentiated tumors often present as large necrotic masses with ill-defined margins on CT, mimicking pleural mesothelioma or undifferentiated carcinoma." (PMID 40978036, 2025). "Here, we present two specimens of SMARCA4-deficient undifferentiated carcinomas of the esophagus and their diagnostic challenges." (PMID 38497146, 2024). "It is important to distinguish SMARCA4-deficient uterine sarcoma from undifferentiated carcinomas, which can occasionally lose SMARCA4 expression." (PMID 39064514, 2024). "Decreased expression of PCK was observed in 58.6% (17/29) of gastric SMARCA4-deficient undifferentiated carcinomas." (PMID 38090508, 2023). "SMARCA4-deficient undifferentiated carcinoma was composed mainly of poorly adhesive rhabdoid cells with eosinophilic cytoplasm arranged in a diffuse pattern." (PMID 34513665, 2021). "The loss of SMARCA4 expression has been reported occasionally in undifferentiated carcinomas with rhabdoid features in the small intestine and stomach." (PMID 33435234, 2021). "Possible mechanisms underlying the transition from differentiated to undifferentiated carcinoma include the acquisition of mutations in SMARCA4, ARID1B, CTNNB1, PPP2R1A or TP53136." (PMID 30550483, 2019). "SMARCA4 mutations have been described in a small subset of SCLC but may also reflect SMARCA4-deficient undifferentiated carcinomas, a recently defined entity." (PMID 41373665, 2025). "Patients with undifferentiated carcinoma of the gastrointestinal (GI) tract exhibiting loss of SMARCA4 expression demonstrated significantly poorer overall survival (p = 0.028) and disease-free survival (p = 0.006) compared to those with SMARCA4 expression." (PMID 38877473, 2024). "Another study reported a rare synchronous malignant gastrointestinal neuroectodermal tumor and SMARCA4-deficient undifferentiated carcinoma in the small intestine that showed complete SMARCA4 deficiency with SMARCA4 frame-shift mutation [c.4882_4886dup(p.Lys1630fs)." (PMID 38877473, 2024). "The specimen was reported as a SMARCA4-deficient undifferentiated carcinoma of the esophagus." (PMID 38497146, 2024). "Here, we describe a case of SMARCA4 (BRG1)-deficient undifferentiated carcinoma of gallbladder." (PMID 37456262, 2023). "SMARCA4 (BRG1)-deficient undifferentiated carcinoma is a rare and highly aggressive malignancy." (PMID 37456262, 2023). "Two distinct entities, GNET and SMARCA4-deficient undifferentiated carcinoma, were identified." (PMID 34513665, 2021). "Meanwhile, SMARCA4-deficient undifferentiated carcinoma is a rarely reported entity with highly aggressive behavior that may involve the ovary, lung, gastrointestinal (GI) tract, endometrium and other organs." (PMID 34513665, 2021). "Inactivation of SMARCA4 (BRG1) has been suggested to be involved in the pathogenesis of some undifferentiated carcinomas of the lung, ovary, gastrointestinal tract, uterus, and other organs." (PMID 39723373, 2024). "SMARCA4-deficiency was mostly found in teratocarcinosarcoma while SMARCB1-deficient tumors were associated with undifferentiated carcinoma and non-keratinizing squamous cell carcinoma." (PMID 36937407, 2023). "Since SMARCA4-DTT is often misdiagnosed as a carcinoma of unknown primary origin or as an undifferentiated carcinoma, nuclear medicine clinicians should include this disease in their list of differential diagnoses." (PMID 34181162, 2021).
undifferentiated carcinoma (continued). "Immunohistochemical loss of SMARCA2 and SMARCA4 can occur simultaneously or independently, and undifferentiated carcinomas with SMARCA2 loss without SMARCA4 loss have also been reported, suggesting that SMARCA2 loss was also involved in the process of tumor dedifferentiation." (PMID 36464671, 2022). "SMARCB1 or SMARCA4 loss was not restricted to rhabdoid/undifferentiated carcinoma." (PMID 33481850, 2021). "In this study, SMARCA2 was the most frequently lost subunit, while it was not thoroughly investigated in undifferentiated carcinomas compared with SMARCA4." (PMID 36464671, 2022).
glioma (25 papers, 2013 to 2025). A benign or malignant brain and spinal cord tumor that arises from glial cells (astrocytes, oligodendrocytes, ependymal cells). "Altered SMARCA4 expression has been linked to medulloblastoma, low-grade gliomas such as oligodendroglioma, high-grade gliomas such as glioblastoma and atypical/teratoid rhabdoid tumours." (PMID 37433987, 2023). "SMARCA4 is a recurrently mutated gene in multiple types of brain cancer including medulloblastoma, glioma, and atypical teratoid/rhabdoid tumours." (PMID 37433987, 2023). "The frequency of SMARCA4 mutations in gliomas appear to differ between low and high-grade tumours." (PMID 37433987, 2023). "SMARCA4 was found to maintain gliomas in an undifferentiated stem cell state, regulate genes involved in cell growth and extracellular matrix, and promote tumor growth in vivo in an H3K27M-dependent manner." (PMID 38390898, 2024). "We demonstrate that H3K27M gliomas show increased protein levels of the SWI/SNF complex ATPase subunits SMARCA4 and SMARCA2, and the PBAF component PBRM1." (PMID 37094128, 2023). "On the other hand, Hoxa5 and Fabp4, both associated with increased malignancy in gliomas, were upregulated in MYC/SMARCA4 tumors." (PMID 37919824, 2023). "SMARCA4 also plays a fundamental role in maintaining glioma-initiating cells that present stem-like molecular features." (PMID 36674511, 2023). "A 2013 study investigated the association of various genetic variants of SMARCA4 and SMARCA2 with the risk of glioma subtype and mortality." (PMID 37433987, 2023). "In contrast, SMARCA4 may also be an oncogene in liver hepatocellular carcinoma, lower-grade glioma, and pan-cancer." (PMID 33407425, 2021). "SMARCA4-containing BAF complex maintains glioma stem cells in a cycling, oligodendrocyte precursor cell (OPC)-like state, and disruption of SMARCA4 promotes the progression of differentiation along the astrocytic lineage." (PMID 36674511, 2023). "The 2016 WHO Classification of Tumors of the Central Nervous System defined AT/RT by alterations of either INI1 protein (SMARCB1 gene), or rarely, BRG1 protein (SMARCA4 gene)." (PMID 30547013, 2018). "The absence of SMARCA4 (also known as BRG1) could prematurely stagnate Schwann cell differentiation, and inhibit the proliferation, migration and invasion of glioma cells." (PMID 36046506, 2022). "We demonstrate that a PROTAC tool compound AU-15330 that simultaneously degrades the ATPases SMARCA4 and SMARCA2 and PBRM1 selectively kills H3.3K27M but not H3WT glioma cell lines." (PMID 37094128, 2023).
hepatocellular carcinoma (24 papers, 2017 to 2025). A malignant tumor that arises from hepatocytes. "However, our comprehensive analyses revealed aberrant overexpression of GAS5 in various cancers, with a direct association with SMARCA4 in hepatocellular carcinoma (HCC)." (PMID 40451925, 2025). "BET inhibitor has also emerged as a promising drug for the treatment of SMARCA4-deficient hepatocellular carcinoma based on preclinical studies, indicating that this particular subtype of cancer patients may benefit from precision targeted therapy." (PMID 34675941, 2021). "Additionally, we observed that liver carcinoma patients carrying a mutation in SMARCA4 have a poor prognosis." (PMID 29030609, 2017). "The control of 4-HNE metabolism by SMARCA4 is important in promoting the survival of hepatocellular carcinoma cells." (PMID 39723384, 2024). "Decreased 4-HNE accumulation is a poor prognostic factor in hepatocellular carcinoma, and intracellular 4-HNE metabolism is controlled by SMARCA4." (PMID 39723384, 2024).